ESR2 (estrogen receptor 2)
Description:
Nuclear hormone receptor. Binds estrogens with an affinity similar to that of ESR1/ER-alpha, and activates expression of reporter genes containing estrogen response elements (ERE) in an estrogen-dependent manner. [Isoform 2]: Lacks ligand binding ability and has no or only very low ERE binding activity resulting in the loss of ligand-dependent transactivation ability.
Synonyms: ER-beta; ESTRB; NR3A2; Erb; ESR-BETA; ESRB; ODG8
Tractability: Small molecule: an approved drug acts on it; a structure with a bound ligand is known; a high-quality ligand is known; it has a high-quality binding pocket; it belongs to a druggable protein family. PROTAC: a small molecule that binds it is known. Other modalities: an approved drug acts on it.
Target class: Nuclear hormone receptor subfamily 3; Transcription factor; Nuclear receptor; Nuclear hormone receptor subfamily 3 group A; Nuclear hormone receptor subfamily 3 group A member 2
Chemical probes: CHEMBL1782957, GW5638, GW7604, Licoflavone C, PD080757, PD081843, PD085111, PD085179, PD134234, PD134235, estriol
Safety:
Unwanted effects reported when the protein is acted on. In parentheses: how it was acted on, where the effect was seen, and who reports it.
bone density loss (source: ClinPGx)
tamoxifen-induced increase in triglycerides (source: ClinPGx)
Gene: Protein-coding gene on chromosome 14 (64,084,232 to 64,338,112, reverse strand). Ensembl gene ENSG00000140009.
Subcellular location: Nucleus
Subcellular location (Human Protein Atlas): Nucleoplasm; Vesicles
Pathways (Reactome):
Signal Transduction: ESR-mediated signaling; Extra-nuclear estrogen signaling; PI5P, PP2A and IER3 Regulate PI3K/AKT Signaling; PIP3 activates AKT signaling
Disease: Constitutive Signaling by Aberrant PI3K in Cancer
Gene expression (Transcription): Nuclear Receptor transcription pathway
Gene Ontology:
Molecular function: enzyme binding; estrogen response element binding; nuclear estrogen receptor activity; nuclear receptor activity; protein binding; RNA polymerase II cis-regulatory region sequence-specific DNA binding; DNA binding; DNA-binding transcription factor activity, RNA polymerase II-specific; nuclear steroid receptor activity; receptor antagonist activity; steroid binding; DNA-binding transcription factor activity; sequence-specific DNA binding; zinc ion binding
Biological process: negative regulation of transcription by RNA polymerase II; positive regulation of DNA-templated transcription; cell-cell signaling; estrogen receptor signaling pathway; negative regulation of cell growth; regulation of DNA-templated transcription; regulation of transcription by RNA polymerase II; signal transduction; cellular response to estradiol stimulus
Cellular component: mitochondrion; nucleoplasm; nucleus; chromatin
Genetic constraint (gnomAD): Loss-of-function variants: 36 observed, 47.45 expected, observed/expected ratio (o/e) 0.76, 90% interval 0.58 to 1. The upper end of that interval is the gene's LOEUF score, 1, which puts it in group 4 of 6, group 1 being the genes least tolerant of losing a copy. Missense variants: 668 observed, 657.98 expected, observed/expected ratio (o/e) 1.02, 90% interval 0.95 to 1.08. Synonymous variants: 295 observed, 255.83 expected, observed/expected ratio (o/e) 1.15, 90% interval 1.05 to 1.27.
Homologues: Orthologues: chimpanzee ESR2 (99% identical), macaque ESR2 (97% identical), dog ESR2 (89% identical), mouse Esr2 (89% identical), guinea pig ESR2 (88% identical), pig ESR2 (86% identical), rabbit ESR2 (82% identical), rat Esr2 (82% identical), tropical clawed frog esr2 (69% identical), zebrafish esr2b (55% identical), zebrafish esr2a (54% identical), Drosophila melanogaster ERR (23% identical). Paralogues in human: ESR1 (45% identical), ESRRG (28% identical), ESRRB (28% identical), ESRRA (27% identical), NR3C2 (24% identical), PGR (24% identical), NR3C1 (24% identical), AR (23% identical).
Diseases named in the same sentence as ESR2 in open-access papers:
ESR2 is named in the same sentence as 476 diseases in open-access papers, as found by Europe PMC text mining. Sharing a sentence is not in itself a finding about the gene and the disease. The quoted sentences say what the papers report.
breast cancer (647 papers, 2001 to 2026). A primary or metastatic malignant neoplasm involving the breast. "Pharmacophore analysis is integral to drug design, and in this study, it emerges as a crucial component for understanding the molecular characteristics of the ESR2 mutant proteins associated with breast cancer." (PMID 39101505, 2024). "In conclusion, our comprehensive computational study focused on understanding the structural implications of ESR2 mutations and exploring potential drug candidates for breast cancer therapy." (PMID 39101505, 2024). "Breast cancer, a leading cause of female mortality, is closely linked to mutations in estrogen receptor beta (ESR2), particularly in the ligand‐binding domain, which contributed to altered signaling pathways and uncontrolled cell growth." (PMID 39101505, 2024). "This study investigated the expression of MET, ESR1, and ESR2 genes and their association with clinicopathologic characteristics and clinical outcomes in patients with breast cancer." (PMID 39742369, 2024). "Our results disclosed that higher expression of PTGS2/ESR2/EGFR/JUN/MMP2 genes’ signature associated with the most aggressive breast cancer subtypes donating by basal breast cancer (P < .00001) and the ER-negative breast tumors ( P < .00001)." (PMID 39707884, 2024). "We genotyped the ESR2 variants (rs1256049, rs4986938, and rs1256030) in breast cancer (BC) patients and in healthy women." (PMID 35573183, 2022). "In conclusion, we have characterized the expression of ESR2 across the largest population-based breast cancer cohort to date, and described its association to clinicopathological parameters and patient outcomes." (PMID 35304506, 2022). "Mutations in the ESR2 (gene encoding for ERβ) have been primarily involved in breast cancer development." (PMID 39483629, 2021). "Hypermethylation of the ON promoter was shown to be the cause of ESR2 gene silencing in breast cancer." (PMID 33562134, 2021). "They highlighted the importance of translational regulation in determining expression levels of ESR2 variants, including ERβ5, in breast cancer cell lines." (PMID 31778358, 2020). "In another meta-analysis, including 22833 cases and 30319 controls, results showed that ESR2 rs4986938 polymorphism was associated with decreased breast cancer and ethnicity subgroup analysis observed a decreased risk in both Asian and Caucasian descendent." (PMID 31523634, 2019). "Previous study in woman suffer from breast cancer suggested that One haplotype of the ESR2 gene was associated with breast cancer risk." (PMID 30806067, 2019). "Though we did not identify ESR2, a central protein in this estrogen receptor network, it has been shown to associate with neurofibromin in breast cancer cells by AP-MS with tagged ESR2." (PMID 31466283, 2019). "In a previous meta-analysis, including 22833 cases and 30319 controls, ESR2 rs4986938 was likely to be related to breast cancer risk, and only contained one type of tumor." (PMID 31523634, 2019). "An earlier meta-analysis reported that ESR2 rs4986938 was associated with the risk of breast cancer (BC)." (PMID 31523634, 2019). "Continuous variable analysis of ESR1_TA, ESR2_CA, and AR_CAG alleles and breast cancer risk in African American and Nigerian women." (PMID 22792352, 2012). "Among all participants, the ESR2 *5772G allele was associated with a statistically significant decrease in the risk of breast cancer among women with BBD (OR 0.38; 95% CI 0.15, 0.96)." (PMID 16808847, 2006). "Several studies have investigated the associations between polymorphisms in the ESR1 and ESR2 genes and the risk of breast cancer among average-risk women and have reported mixed results." (PMID 16808847, 2006). "The aim of the present study was to analyze the associations between genetic polymorphisms in three estrogen metabolizing enzymes (COMT, CYP1A1, CYP1B1) and the two estrogen receptors (ESR1, ESR2) and the risk of developing breast cancer among women with BBD." (PMID 16808847, 2006).
breast cancer (continued). "Among all participants, the ESR2 *5772G allele was associated with a significant decrease in the risk of breast cancer among women with BBD (Odds Ratio (OR) 0.38; 95% Confidence Interval (CI) 0.15, 0.96)." (PMID 16808847, 2006). "Importantly, our pan-cancer survival analysis revealed tumor-type-specific prognostic patterns: ESR2 alterations were linked to worse outcomes in breast cancer but better outcomes in ovarian and endometrial cancers." (PMID 41153361, 2025). "Taken together, our results indicate that ESR2 is generally expressed at low levels in breast cancer but associated with improved overall survival and may be related to immune response modulation." (PMID 35304506, 2022). "Additionally, BPA lowers Esr1 (ERα) and augments Esr2 (ERβ), whose expression is linked to increased risk of breast cancer." (PMID 33330580, 2020). "Expression of mRNA for COX2, P16/INK4A, and KI67 (encoded by PTGS2, CDKN2A, MKI67, respectively) and estrogen receptor beta (ERβ, encoded by ESR2) were analyzed because prior studies suggested these as biomarkers of AH at greater risk of progression to breast cancer." (PMID 31248446, 2019). "Next, near this known biomedical SNP marker rs35036378, we found the unannotated SNP rs766797386, which can also decrease expression of the human ESR2 gene and thus cause an ESR2-deficient primary pT1 tumor requiring prophylaxis by tamoxifen against breast cancer." (PMID 29504899, 2018). "In the present study, we aimed to investigate whether ESR1_TA, ESR2_CA, and AR_CAG could be breast cancer susceptibility markers in African American (AA) and Nigerian (NG) women." (PMID 22792352, 2012). "Moreover a study by MARIE-GENICA Consortium suggested that higher risk were observed in subjects having combined genotypes of both ESR1 and ESR2 genes which modified risk associated with estrogen monotherapy used in breast cancer." (PMID 22808109, 2012). "ESR2 has previously been suggested to harbor common breast cancer predisposing variants, and ESR2 variation has been suggested to influence the development of breast cancer also by in vitro studies." (PMID 22737080, 2012). "Microsatellites in the estrogen receptor (ESR1, ESR2) and androgen receptor (AR) genes have been hypothesized to be predisposing factors for breast cancer but the mechanisms are unknown." (PMID 22792352, 2012). "The findings of this study indicate that specific polymorphisms in the CYP1B1, ESR1, and ESR2 genes may play a role in progression of BBD to breast cancer among Caucasian women." (PMID 16808847, 2006). "The results indicate that specific polymorphisms in the CYP1B1, ESR1, and ESR2 genes may play a role in progression of BBD to breast cancer among Caucasian women." (PMID 16808847, 2006). "In addition, results from this study suggest that women with BBD who carry the ESR2 *5772A>G polymorphism or the ESR1 – 104062C>T polymorphism are at decreased risk of developing breast cancer." (PMID 16808847, 2006). "The strong enrichment for mammary gland morphogenesis (GO) and breast cancer pathways (KEGG) further confirmed ESR2 nsSNPs’ roles in oncogenic transformation and tissue homeostasis." (PMID 41153361, 2025). "As a member of the nuclear receptor superfamily, ER exists in two primary isoforms: ERα (encoded by ESR1) and ERβ (encoded by ESR2), with ERα being the predominant and clinically relevant isoform in most hormone-positive breast cancers." (PMID 40983817, 2025). "In light of this, we aimed to assess the expression pattern of ER genes, ESR1 and ESR2, with MET and further explore their association with clinicopathologic features, prognostic factors, and clinical outcomes in breast cancer." (PMID 39742369, 2024). "Through pharmacophore modeling and virtual screening, we aim to identify shared pharmacophoric regions, paving the way for precision inhibition and the development of promising therapeutic targets against mutant ESR2 in breast cancer." (PMID 39101505, 2024).
breast cancer (continued). "According to the findings, MYLK and estrogen receptor gene expression had a positive correlation with ESR1 in patients with Her2 and with ESR2 expression in patients with Luminal A breast cancer." (PMID 39596804, 2024). "Breast cancer patients with elevated expression of PTGS2/ESR2/EGFR/JUN/MMP2 genes’ signature displayed significantly poor OS (P = 0.026) and DMFS (P = 0.0066) and consequently unfavorable prognosis." (PMID 39707884, 2024). "On the other hand, the VNN1 and ESR2 genes were positively correlated in Basal and Luminal A breast cancer patients." (PMID 39596804, 2024). "Our findings revealed distinct coexpression patterns of MET/ESR1 and MET/ESR2, each correlating with specific clinicopathologic features and clinical outcomes, thereby enriching the prognostic landscape of breast cancer." (PMID 39742369, 2024). "ESR2 gene expression was also negatively correlated in Her2 breast cancer patients, whereas it was positively correlated in Luminal A patients." (PMID 39596804, 2024). "It is vital to identify the likely biological processes and cellular functions by which PTGS2/ESR2/EGFR/JUN/MMP2 genes’ signature exhibited their tumorigenic effect in breast cancer." (PMID 39707884, 2024). "Estrogen receptor alpha (ESR1) and its ligand estradiol (ESR2) is critical for growth of about 70 % of breast cancers." (PMID 38034788, 2023). "In this study, we reported that high ESR2 expression rates have been correlated to decreased overall survival rates in breast cancer patients diagnosed with invasive breast carcinoma." (PMID 35719919, 2022). "In this study we have characterized the expression of ESR2 mRNA using RNA-seq analysis of a large cohort of breast cancer samples from SCAN-B." (PMID 35304506, 2022). "We measured the expression levels of ESR1 and ESR2 genes in immortalized mammary epithelial cells and different breast cancer cell lines." (PMID 35574319, 2022). "In the present study, we showed that in a cohort of 37 metastatic breast cancer patients there was a trend of increased overall survival in ESR2-high-expressing patients compared to ESR2-low-expressing patients." (PMID 35574319, 2022). "Both EC cell lines showed low expression of ESR1 and ESR2 as compared to the T47D breast cancer line used as a positive control." (PMID 36727068, 2022). "Our analyses revealed that ESR2 transcripts are generally much less abundant than ESR1 across all breast cancers." (PMID 35304506, 2022). "To add further clarity to ESR2 in breast cancer, we interrogated a large population-based cohort of primary breast tumors (n = 3207) from the SCAN-B study." (PMID 35304506, 2022). "Regarding breast cancer, ESR2 expression is 2-fold higher in invasive breast carcinoma as compared to normal breast tissues." (PMID 35719919, 2022). "The expression of ESR2 and genes containing ERE-AP1 composite response elements was examined in ERα+ human breast cancer samples to determine the correlation between ESR2 expression and overall survival and that of putative ESR2-regulated genes." (PMID 35574319, 2022). "Correlation of ESR2 expression levels with survival of breast cancer patients was calculated by level of CD8+ T cell infiltration." (PMID 33462142, 2021). "It is also widely believed that ESR2 is closely related to the occurrence and development of breast cancer." (PMID 33868436, 2021). "The estrogen receptor signaling is mediated by estrogen receptors, ESR1 and ESR2, while the majority of breast cancers have disregulated estrogen receptor signaling." (PMID 34055017, 2021). "All patients in the TCGA breast cancer study were divided according to ESR2 expression (higher or lower than mean expression value of all patients)." (PMID 33462142, 2021).
breast cancer (continued). "Estrogen signaling plays a key role in BC carcinogenesis and it is mediated by two receptors belonging to the nuclear receptor superfamily: ERα and ERβ, encoded by the ESR1 and ESR2 genes, respectively, that play opposite roles in hormone-responsive breast cancer progression." (PMID 32260128, 2020). "Given that ESR1 and ESR2 encode for ER-α and ER-β, we investigated the correlation of the estrogen response early score with the expression of ER-α (ESR1) and ER-β (ESR2) genes in large breast cancer cohorts." (PMID 33260779, 2020). "Most previous studies reported estrogen receptors as a prognostic marker for hormone‐related tumors, such as ESR1 in thyroid carcinoma, and ESR1 and ESR2 in ovarian and breast cancer." (PMID 32536040, 2020). "Considered the pathophysiologic functions of CYP19A1 and ESR1/ESR2-mediated signaling pathway in breast cancer seem as more complicated than what we have already known, more precise evaluation will be needed in urgent." (PMID 31741086, 2019). "For example, both Tamoxifen and Diethylstilbestrol target the estrogen receptors ESR1 and ESR2, which are the marker in Breast Cancer ER+." (PMID 29922160, 2018). "The nuclear receptor estrogen receptor 2 (ESR2, ERβ) modulates cancer cell proliferation and tumor growth, exerting an oncosuppressive role in breast cancer (BC)." (PMID 29509190, 2018). "We found the ESR2 promoter frequently methylated in tumor, tumor-adjacent and tumor-distant tissues from breast cancer patients, whereas in normal breast tissues from healthy women, the methylation status was < LOQ (5%)." (PMID 28403857, 2017). "Total PCBs associated with AREG, CYP19A1, ESR2, FOS, KRAS and STC2 genes; PCB 126 associated with AREG, CYP19A1, and STC2 genes and PCB 15 associated with CYP19A1, EGFR, ESR2, FOS, and IGF1 genes overlapped with 17β-estradiol, breast cancer, and endometriosis." (PMID 26512648, 2015). "We began by measuring ESR2 mRNA and ERβ protein levels in response to patient sera in a panel of human breast cancer cell lines representing the four major breast cancer subtypes." (PMID 26709918, 2015). "In our study we found that five common estrogen responsive genes, including CYP19A1 and ESR2 that were associated with all three EDCs-PCBs, phthalates and BPA, breast cancer, and endometriosis." (PMID 26512648, 2015). "Inrecent years, studies have been conducted to evaluate the anti-cancer effect of silybin.We studied the effect of silybin and silybin-phosphatidylcholine on ESR1 and ESR2 geneexpression and viability in the T47D breast cancer cell line." (PMID 24611152, 2014). "Curiously, based on their function both ESR2 and CYP2C19 have long been considered strong candidate genes for breast cancer susceptibility." (PMID 22737080, 2012). "Of the network genes ESR2, STRN and ANKS1B exhibited recurrent disrupting alleles among cancer cases, emphasizing their potential role in breast cancer predisposition." (PMID 22737080, 2012). "The ascertainments of ESR1_TA, ESR2_CA and AR_CAG in breast cancer have also been of scientific interest, especially on AR_CAG." (PMID 22792352, 2012). "For example, the ESR2 and MAPK1 genes in the prostate cancer prediction, and the IL6 and CEBPD in the breast cancer predictions, were associated with several chemicals for each of the diseases." (PMID 20459635, 2010). "In analogy, ESR2 is - apart from breast cancer epithelial tumor cells - also expressed in adjacent infiltrating lymphocytes, fibroblasts, and endothelial cells." (PMID 21122099, 2010).